ENSG00000301059 (novel transcript)
Synonyms: LOC105377563
Gene: Long non-coding RNA gene on chromosome 4 (178,813,017 to 178,843,614, forward strand). Ensembl gene ENSG00000301059.
Diseases named in the same sentence as ENSG00000301059 in open-access papers:
ENSG00000301059 is named in the same sentence as 1 disease in open-access papers, as found by Europe PMC text mining. Sharing a sentence is not in itself a finding about the gene and the disease.
ENSG00000301059 shares sentences with these, for which no sentence is quoted: breast carcinoma (1 paper).